TRIM36 (tripartite motif containing 36)
Description:
E3 ubiquitin-protein ligase which mediates ubiquitination and subsequent proteasomal degradation of target proteins including CTNNB1, FOXA2 and AKT1. Involved in chromosome segregation and cell cycle regulation. May play a role in the acrosome reaction and fertilization. Inhibits lung fibroblast proliferation, migration, and differentiation. Mechanistically, mediates 'Lys-48'-linked polyubiquitination of phospho-AKT1, leading to its proteasomal degradation and consequent inhibition of AKT signaling. Promotes apoptosis via inhibition of the Wnt/beta-catenin signaling pathway. Regulates ferroptosis by ubiquitinating and degrading FOXA2.
Synonyms: RBCC728; RNF98; HAPRIN; ANPH; ANPH1
Tractability: Antibody: its Gene Ontology location is reachable by antibodies, with high confidence. PROTAC: ubiquitination databases record sites on it; its protein half-life has been measured.
Gene: Protein-coding gene on chromosome 5 (115,124,762 to 115,180,546, reverse strand). Ensembl gene ENSG00000152503.
Subcellular location: Cytoplasm; Cytoplasmic vesicle, secretory vesicle, acrosome; Cytoplasm, cytoskeleton
Subcellular location (Human Protein Atlas): Cytosol; Plasma membrane
Pathways (Reactome):
Immune System: Antigen processing: Ubiquitination & Proteasome degradation
Gene Ontology:
Molecular function: protein binding; ubiquitin protein ligase activity; alpha-tubulin binding; ubiquitin-protein transferase activity; zinc ion binding
Biological process: mitotic cytokinesis; proteasome-mediated ubiquitin-dependent protein catabolic process; protein K48-linked ubiquitination; protein polyubiquitination; regulation of microtubule cytoskeleton organization; spindle organization; acrosome reaction
Cellular component: cytoplasm; cytosol; acrosomal vesicle; cytoskeleton
Genetic constraint (gnomAD): Loss-of-function variants: 36 observed, 63.68 expected, observed/expected ratio (o/e) 0.57, 90% interval 0.43 to 0.75. The upper end of that interval is the gene's LOEUF score, 0.75, which puts it in group 3 of 6, group 1 being the genes least tolerant of losing a copy. Missense variants: 815 observed, 794.28 expected, observed/expected ratio (o/e) 1.03, 90% interval 0.97 to 1.09. Synonymous variants: 280 observed, 264.93 expected, observed/expected ratio (o/e) 1.06, 90% interval 0.96 to 1.17.
Homologues: Orthologues: macaque TRIM36 (99% identical), chimpanzee TRIM36 (98% identical), dog TRIM36 (95% identical), pig TRIM36 (95% identical), rat Trim36 (92% identical), mouse Trim36 (92% identical), guinea pig TRIM36 (92% identical), rabbit TRIM36 (90% identical), tropical clawed frog trim36 (70% identical), zebrafish trim36 (62% identical). Paralogues in human: TRIM46 (44% identical), TRIM9 (24% identical), TRIM67 (24% identical), TRIM33 (16% identical), TRIM24 (15% identical), TRIM37 (14% identical), MID1 (14% identical), TRIM2 (13% identical), TRIM71 (13% identical), TRIM8 (12% identical), TRIM3 (12% identical), MID2 (12% identical), and 68 more.
Diseases named in the same sentence as TRIM36 in open-access papers:
TRIM36 is named in the same sentence as 26 diseases in open-access papers, as found by Europe PMC text mining. Sharing a sentence is not in itself a finding about the gene and the disease. The quoted sentences say what the papers report.
prostate carcinoma (11 papers, 2014 to 2025). A carcinoma that arises from epithelial cells of the prostate gland. "Reduced levels of TRIM36 are associated with advanced stages of prostate cancer and TRIM36 was reported to be an independent predictor of survival in prostate cancer patients." (PMID 32226386, 2020). "Of these 8 secretion-related genes, 5 genes (FKBP1B, SCIN, SMPD3, STEAP2, and TRIM36) has been associated with prostate cancer and hyperplasia." (PMID 26113971, 2015). "TRIM36 expression was significantly associated with the Gleason score (P = 0.005), delayed prostate cancer cell cycle progression and inhibited cell proliferation in vitro and in vivo, and these effects were mediated via inhibition of the MAPK/ERK phosphorylation pathway." (PMID 29449534, 2018). "Among the TRIM family proteins regulating carcinogenesis in prostate cancer, TRIM36 is a unique protein since this protein is both androgen-dependent and also acts as a tumor suppressor." (PMID 40723250, 2025). "The E3 ligase TRIM36 ubiquitinates HK2 to inhibit the neuroendocrine differentiation (NED) of prostatic cancer." (PMID 39048965, 2024). "TRIM36 can enhance the suppression effect of anti-androgen on prostate cancer by reducing the phosphorylation of proteins in the MAPK pathway." (PMID 37520369, 2023). "In prostate cancer, the results are less clear as both up- and down-regulation of TRIM36 have been reported." (PMID 35053362, 2022). "In one of these reports, TRIM36 was shown to be upregulated in prostate cancer patients and to delay the cell cycle of prostate cancer cells in vitro and in vivo." (PMID 35053362, 2022). "A previous study has linked TRIM36 expression to cell cycle progression and proliferation in NIH3T3 cells and prostate cancer cells." (PMID 32802046, 2020). "Recently, TRIM36 has been identified as an androgen-responsive gene, and its tumor-suppressive role has been reported in prostate cancer." (PMID 32802046, 2020). "TRIM36 expression is increased in response to androgen and has a prostate cancer suppressive role that includes inhibiting prostate cancer cell proliferation and migration while promoting prostate cancer cell death." (PMID 32226386, 2020). "The enhanced expression of TRIM36 due to AR signaling in prostate cancer is considered to be a reasonable explanation for this phenomenon." (PMID 29449534, 2018). "Collectively, TRIM36 is a novel androgen-responsive gene, and it dramatically enhanced the efficacy of anti-androgen drugs against prostate cancer." (PMID 29449534, 2018). "In conclusion, we found that TRIM36 is a novel androgen-responsive gene that enhanced the efficacy of anti-androgen drugs against prostate cancer." (PMID 29449534, 2018). "High levels of the expression of TRIM36 were observed in the AR-positive prostate cancer cell lines (LNCAP and C4-2), whereas RWPE-1 cells rarely exhibited expression of TRIM36." (PMID 29449534, 2018). "With ChIP-chip and CAGE (cap analysis of gene expression) analysis, which are advanced high-throughput techniques, several new AR target genes, including TRIM36, have been identified in the whole genome of prostate cancer cells." (PMID 29449534, 2018). "TRIM36 was reported as a novel androgen signaling target gene and is upregulated in prostate cancer." (PMID 29449534, 2018). "To analyze the function of TRIM36 in PCa, we determined TRIM36 protein expression in 95 cases of prostate cancer." (PMID 29449534, 2018). "Additionally, studies have shown that TRIM36 can enhance the efficacy of anti-androgen drugs in treating prostate cancer." (PMID 39048965, 2024). "Tripartite motif protein 36 (TRIM36) plays a tumor-suppressive role in prostate cancer." (PMID 32802046, 2020). "Like TRIM36, expression TRIMs 16 and 29 is decreased in prostate cancer, suggesting that these proteins may act as tumor suppressors in normal prostate tissue." (PMID 32226386, 2020).
prostate carcinoma (continued). "However, TRIM36 has been reported to be upregulated in primary prostate cancer, and this result was also confirmed in our PCa cohort." (PMID 29449534, 2018). "IHC of the prostate cancer tissues revealed the same pattern of AR and TRIM36 staining." (PMID 29449534, 2018). "Therefore, adding TRIM36 during androgen deprivation therapy (ADT) could be a novel therapeutic approach to better suppress castration-resistant prostatic cancer." (PMID 39048965, 2024). "Importantly, we found that this suppression of prostate cancer cell growth could be enhanced after reversing the expression of TRIM36 in vitro and in vivo, which suggested that TRIM36 may increase the anti-androgen sensitivity in prostate cancer." (PMID 29449534, 2018). "TRIM36 can also act as a putative tumor suppressor by attenuating MAPK/ERK signaling pathways and regulating apoptosis-related pathways in prostate cancer." (PMID 31820796, 2019). "It has been reported that negative TRIM36 expression could be used as a prognostic indicator of the biochemical recurrence-free survival in prostate cancer." (PMID 32802046, 2020).
ovarian carcinoma (3 papers, 2014 to 2021). A malignant neoplasm originating from the surface ovarian epithelium. "Recent studies have revealed that hypermethylation of TRIM36 appears in endometriosis and associated ovarian carcinomas and neuroblastoma tumors, which indicates that TRIM36 hypermethylation might be involved in cancer development." (PMID 29449534, 2018). "Nonetheless, TRIM36 may still be lowly expressed in PC despite active AR signaling, which could be mediated through TRIM36 promoter hypermethylation, as it has been reported in ovarian cancer (OC) and neuroblastoma." (PMID 34208621, 2021).
colorectal cancer (2 papers, 2023 to 2025). A primary or metastatic malignant neoplasm that affects the colon or rectum. "Using qRT‐PCR, we detected the expression levels of PJA2 and TRIM36 mRNA in 20 pairs of colorectal cancer tissue samples from our center and found that the expression of PJA2 in colorectal cancer tissues was more significantly different." (PMID 39928532, 2025).
esophageal cancer (2 papers, 2020 to 2022). A primary or metastatic malignant neoplasm involving the esophagus. "For example, TRIM36 expression has been reported to correlate with the size, stage, lymph node metastasis, and β-catenin expression of esophageal cancer." (PMID 36588538, 2022). "However, there is little information on the clinical relevance of TRIM36 expression in esophageal cancer (ESCA)." (PMID 32802046, 2020).
gastric cancer (2 papers, 2024 to 2025). A primary or metastatic malignant neoplasm involving the stomach. "High TRIM36 expression correlated with enhanced radiosensitivity in gastric cancer, with higher OS rates noted among irradiated patients with elevated TRIM36 levels." (PMID 40936722, 2025). "In gastric cancer, high expression of TRIM36 can increase the OS rate in gastric cancer patients receiving radiotherapy." (PMID 39768197, 2024).
neuroblastoma (2 papers, 2021 to 2024). Neuroblastoma (NB) is the most common solid, extracranial childhood tumor. "Studies have shown that CDK5R2 CYP26B1, DCAF8L1, PAGE1, and TRIM36 can be used to construct prognostic models or prognostic biomarker for HCC, rectal cancer, neuroblastoma, etc." (PMID 38649860, 2024).
anencephaly (1 paper, 2025). A rare neural tube defect during pregnancy, resulting in the absence of a large portion of the brain and skull in the fetus. "In particular, Singh and colleagues detected the homozygous missense variant c.1522C>A; p.(Pro508Thr) in the TRIM36 gene in a fetus with anencephaly conceived by a couple of Indian cousins." (PMID 41008661, 2025). "The association between biallelic causative variants in the TRIM36 (MIM*609317, TRIPARTITE MOTIF-CONTAINING PROTEIN 36) and in the NUAK2 (MIM*608131, NUAK FAMILY, SNF1-LIKE KINASE, 2) genes with anencephaly remains provisional, as it has been described in one family each." (PMID 41008661, 2025).
cardioembolic stroke (1 paper, 2023). "A genetic polymorphism at another TRIM family member (TRIM36) has recently been associated with cardioembolic stroke, a subtype of ischemic stroke, in a genome-wide association analysis." (PMID 37370144, 2023).
colon cancer (1 paper, 2023). "Taken together, all these data suggested that TRIM36 could directly interact with FOXA2, and induce its K48‐linked polyubiquitination for its protein degradation in colon cancer cells." (PMID 37875418, 2023).
liver cancer (1 paper, 2022). An epithelial or non-epithelial malignant neoplasm that arises from the liver. "Western blotting revealed the expression levels of TRIM36 in the normal control liver cell line LO2 and the liver cancer cell lines HCCLM3, Huh7, Hep G2, PLC/PRF/5, and MHCC-97H." (PMID 36068629, 2022).
male infertility (1 paper, 2012). The inability of the male to effect fertilization of an ovum after a specified period of unprotected intercourse. "Functionally, FKBP6 encodes a member of FK506 binding protein family and has been associated with male infertility in humans and mice, while TRIM56 belongs to tripartite motif-containing gene family, members of which, like TRIM36 (alias HAPRIN), are involved in acrosome reaction of mammalian sperm." (PMID 23284302, 2012).
retinal disease (1 paper, 2012). "Based on putative function and/or involvement in retinal disease, we selected 16 genes – Bach2, Cdr2, Dusp12, Esrrb, Gpsm2, Haus1, Kdm5b, Lman1, Lrp11, Lrrc2, Ncoa2, Plekha2, Ppargc1b, Trim36, Wisp1 and Zdhhc14." (PMID 22511886, 2012).
tumor (13 papers, 2014 to 2025). "The effect of TRIM36 regulation on tumor properties was assessed in both loss- and gain-of function experiments." (PMID 36068629, 2022). "Here, we provide a comprehensive and detailed molecular portrait of the regulated pathway and mechanism underlying the tumor-suppressive effects of TRIM36 in HCC." (PMID 36068629, 2022). "TRIM36 was initially cloned from the tumor suppressor gene region of chromosome 5q22.3, frequently altered in different types of tumors." (PMID 39205302, 2024). "This analysis identified TRIM36, CYP26B1, PAGE1, CDK5R2, and DCAF8L1 as a molecular signature associated with tumor aggressiveness." (PMID 38649860, 2024). "In line with the TCGA assay results, CRC tumor tissues from our cohort exerted lower TRIM36 protein expression than the paired adjacent normal tissues." (PMID 37875418, 2023). "The results using the TCGA database further indicated that the mRNA expression of TRIM36 was markedly lower in tumor tissues than that in normal tissues." (PMID 37875418, 2023). "Cells expressing sh-TRIM36 produced significantly larger lesion sizes, tumor volumes, and tumor weights compared to the vector-only control." (PMID 36068629, 2022). "In vivo, sh-TRIM36 treatment significantly inhibited HCC xenograft tumor growth, suggested that TRIM36 functions as a tumor suppressor." (PMID 36068629, 2022). "TRIM36 expression was significantly downregulated in HCC tissues compared to adjacent non-tumor tissues." (PMID 36068629, 2022). "The protein expression of TRIM36 was closely related to tumor size, tumor stage, lymph node metastasis, and vital status." (PMID 32802046, 2020). "TRIM36 protein expression was correlated with tumor size (P = 0.0104), tumor stage (P = 0.0169), lymph node metastasis (P = 0.0021), vital status (P = 0.0443), and β-catenin expression (P = 0.0329)." (PMID 32802046, 2020). "By Fisher's exact test, we found that TRIM36 protein expression was significantly correlated with tumor size (P = 0.0104), tumor stage (P = 0.0169), lymph node metastasis (P = 0.0021), vital status (P = 0.0443), and β-catenin expression (P = 0.0329)." (PMID 32802046, 2020). "TRIM36 is a member of the TRIM family that was cloned from the tumor suppressor gene region located at chromosome 5." (PMID 29449534, 2018). "The expression of TRIM36 was significantly higher in the PCa tissues compared with the adjacent non-tumor tissues." (PMID 29449534, 2018). "Hypermethylation status in TRIM36 was also identified in tumours of lung, breast, liver and ovarian cancer." (PMID 29618728, 2018). "Taken together, these results suggest a possible tumor suppressor role for TRIM36 in HCC." (PMID 36068629, 2022). "Our study is the first to indicate that TRIM36 acts as a tumor suppressor in HCC." (PMID 36068629, 2022). "Tumor tissues were collected for IHC, which confirmed the decreased expression of TRIM36." (PMID 36068629, 2022). "The TRIM36 gene is located on chromosome 5q22.3, a tumor suppressor region." (PMID 36068629, 2022). "Importantly, combining MDV3100 and TRIM36 led to the most significant suppression effects (group 4 vs group 1; 62% decrease in tumor size)." (PMID 29449534, 2018). "The results demonstrated that overexpression of TRIM36 significantly inhibited tumor growth." (PMID 29449534, 2018). "Ninety-two HCC patients (57 men and 35 women) were enrolled in this study, and the expression levels of TRIM36 in HCC tissues and adjacent non-tumor tissues were detected by IHC, showed a significant downregulation in HCC tissues." (PMID 36068629, 2022). "Expressing TRIM36 alone also suppressed the C4-2-GFP tumor growth (group 2 vs group 1; 17% decrease in tumor size)." (PMID 29449534, 2018). "Recognizing the critical role of m1A in tumor progression and prognosis, a reliable prognostic signature based on five DEGs characterizing autophagy among the m1A modification patterns (CDK5R2, CYP26B1, DCAF8L1, PAGE1, and TRIM36) was initially established." (PMID 38649860, 2024).
tumor (continued). "In addition, TRIM36 interacts and suppresses via ubiquitin-mediated degradation the forkhead box factor A2 (FOXA2,), a transcription factor that plays an important role in metabolism and tumor-cell proliferation." (PMID 39205302, 2024).
cancer (5 papers, 2014 to 2024). A tumor composed of atypical neoplastic, often pleomorphic cells that invade other tissues. "FOXA2 suppression by TRIM36 was found to exert an anti-cancer function in colorectal cancer (CRC) by promoting NRF2/GPX4-mediated ferroptosis, emphasizing the potential of targeting the Nrf2/GPX4 pathway for therapeutic interventions in cancer." (PMID 39036600, 2024). "Most HCC tissues exhibited elevated protein levels of CDK5R2, CYP26B1, DCAF8L1, PAGE1, and TRIM36 in comparison to para-carcinoma tissues, as indicated by the results." (PMID 38649860, 2024). "TRIM36 is a microtubular protein acting in the organization of the cytoskeleton and through this function exerting roles in development and possibly in spermatogenesis and cancer." (PMID 35053362, 2022). "Early pilot data from the same investigators suggest that the expression of TRIM36 in cancer cells from men without PSA recurrence is significantly increased, and this condition was identified as a prognostic factor for cancer-specific survival." (PMID 29449534, 2018).
TRIM36 also shares sentences with these, for which no sentence is quoted: Cachexia (1 paper); dementia (1); endometrial cancer (1); endometriosis (1); hepatocellular carcinoma (1); infertile (1); ischemic stroke (1); lymph node metastasis (1); non-small cell lung carcinoma (1); rectal cancer (1); retinal degeneration (1); viral infection (1).